FLI1 (Fli-1 proto-oncogene, ETS transcription factor)
Diseases named in the same sentence as FLI1 in open-access papers (continued):
Sharing a sentence is not in itself a finding about the gene and the disease.
soft tissue tumors (11 papers, 2014 to 2025). "As a result, these considerations can justify the proposal of the screening of EWS/FLI-1 fusion in a larger variety of soft tissue tumors." (PMID 25870707, 2014). "In this study, we tried to detect EWS/FLI-1 fusion in non-Ewing soft tissue tumors, in order to search for a possible new biomarker valuable for investigators." (PMID 25870707, 2014).
scleroderma (10 papers, 2006 to 2025). Scleroderma is a rare autoimmune connective tissue disorder characterized by abnormal hardening of the skin and, sometimes, other organs. "Fli1 expression is markedly downregulated in lesional fibroblasts of patients with scleroderma, and a recent study has linked epigenetic regulation to the repression of the Fli1 gene in scleroderma skin in vivo." (PMID 23041765, 2012). "Most importantly, Fli1 has been shown to be a potent inhibitor of type I collagen production in dermal fibroblasts and persistent downregulation of this transcription factor has been implicated in the pathogenesis of cutaneous fibrosis in scleroderma." (PMID 24058639, 2013). "FLI1 was reported to participate in immune dysregulation in various diseases, including scleroderma and the tumor immune microenvironment in BRCA." (PMID 38448802, 2024). "Abnormal expression of FLI1 in macrophages is involved in multiple immune diseases, with its low expression playing an important role in scleroderma pathogenesis and the development of tissue fibrosis." (PMID 33971970, 2021). "Previous reports suggest a link between dysregulation of Fli1 protein and scleroderma." (PMID 23663495, 2013). "Fli1 protein is markedly down-regulated in lesional fibroblasts from scleroderma patients." (PMID 23663495, 2013). "Epigenetic mechanisms may also be responsible, in part, for the repression of Fli1 gene in scleroderma in vivo and increased methylation of the Fli1 promoter region has been demonstrated in SSc fibroblasts and skin biopsies from SSc patients." (PMID 23663495, 2013). "Although Ets-1 DNA binding activity is increased in scleroderma fibroblasts, the Ets family member Fli-1 has reduced expression in this cell type; however, the consequences of altering the Ets-1/Fli-1 ratios on mesenchymal biology has yet to be fully appreciated." (PMID 16469114, 2006). "Since downregulation of Fli1 may contribute to scleroderma fibrosis, it may not be desirable to employ class I HDAC inhibitors as an anti-fibrotic treatment for scleroderma." (PMID 24058639, 2013). "Our results suggest that Fli1 and CTGF are important mediators of the fibrogenic actions of adenosine and the use of small molecules such as adenosine A2A receptor antagonists may be useful in the therapy of dermal fibrosis in diseases such as scleroderma." (PMID 23663495, 2013).
colon carcinoma (9 papers, 2010 to 2024). "FLI1 is known to be downregulated in colon adenocarcinomas and is associated with colon cancer progression." (PMID 31900418, 2020). "We also found hypermethylation of colon adenocarcinoma and lung adenocarcinoma, specifically in two CpG loci associated with FLI1: cg11017065 (colon cancer) and cg04691908 (lung adenocarcinoma)." (PMID 31900418, 2020). "A ceRNA network targeting FLI1 has also reported in other types of cancers, including the miR-33b/FLI1 axis in hepatocellular carcinoma and the miR-145/FLI1 axis in colon cancer." (PMID 38448802, 2024). "By targeting the oncogenic FLI1, miR-145 suppresses the growth of colon cancer cells and sensitizes them to 5-fluorouracil." (PMID 37513415, 2023). "Circular-RNA friend leukemia virus integration 1 (circ-FLI1; hsa_circ_0000370) is a noninvasive biomarker for the diagnosis of colon carcinoma (CC)." (PMID 35647294, 2022). "miR-145 also inhibits colon cancer cells’ proliferation and sensitizes them to 5-fluorouracil by targeting oncogenic FLI1." (PMID 25928322, 2015). "In addition, miR-145 may also block the expression of Fli-1 and Bcl-2 in colon cancer cells." (PMID 24923427, 2014). "We have demonstrated that miR-145 targets a putative binding site in the 3'-UTR of the Friend leukemia virus integration 1 (Fli-1) gene, and its abundance is inversely related with Fli-1 expression in colon cancer tissues (data not shown)." (PMID 20687965, 2010).
ovarian carcinoma (9 papers, 2009 to 2025). A malignant neoplasm originating from the surface ovarian epithelium. "Therefore, Fli-1 expression is highly associated with the survival in the patients with ovary cancer." (PMID 24923303, 2014). "Patients with higher FLI-1 expression in ovarian cancer, astrocytoma, non-small cell lung cancer, plasmablastic lymphoma and nasopharyngeal carcinoma have poor overall survival (OS)." (PMID 39107790, 2024). "In ovarian carcinoma, FLI-1 is expressed in 74% of cases and is specifically confined to malignant cells." (PMID 38280044, 2024). "Its overexpression is intimately related to malignant phenotypes and poor clinical outcome, suggesting that Fli-1 is a potential prognostic marker and therapeutic molecular target in ovarian cancer." (PMID 24923303, 2014). "This study revealed that Fli-1 played an essential role in the development and progression of ovarian cancers." (PMID 24923303, 2014). "In the present study, Fli-1 expression was mainly found in the cytoplasm of ovarian cancer tissues and SKOV3 cells." (PMID 24923303, 2014). "Immunohistochemical staining revealed that Fli-1 was generally expressed in the cytoplasm of ovarian cancer cells with various intensities." (PMID 24923303, 2014). "Cell proliferation and migration assay were used to explore the function of Fli-1 in ovarian cancer cells." (PMID 24923303, 2014). "Fli-1 protein expression was evaluated by immunohistochemistry in 104 primary epithelial ovarian cancer (EOC) patients with known follow-up data and 20 controls." (PMID 24923303, 2014). "However, a larger cohort of patients with ovarian cancer and other cancer types is still required to further define the clinical significance of Fli-1 and its prognostic value in ovarian cancers in the future." (PMID 24923303, 2014). "If high Fli-1 expression can be further confirmed to indicate poor prognosis, as suggested in this report, it may serve as an important prognostic marker and an attractive therapeutic target in ovarian cancer." (PMID 24923303, 2014). "In a previous study, Fli-1 knockdown reduced ovarian cancer cell proliferation but did not affect tumor metastasis." (PMID 28418872, 2017). "Functionally, we found knocking-down of Fli-1 reduced ovarian cancer cell proliferation, but did not affect tumor metastasis." (PMID 24923303, 2014).
small cell lung carcinoma (9 papers, 2016 to 2024). Small cell lung cancer (SCLC) is a highly aggressive malignant neoplasm, accounting for 10-15% of lung cancer cases, characterized byrapid growth, and early metastasis. "Other studies have reported significantly upregulated levels of FLI1 in small cell lung cancer (SCLC) tissues compared to NSCLC and normal lung tissues." (PMID 34281588, 2021). "FLI1 acts as a novel oncogenic diver to promote the metastasis of small cell lung cancer (SCLC)." (PMID 33014809, 2020). "For instance, FLI1 exonic circular RNAs (FECR) could be transferred by serum-derived exosomes in small cell lung cancer patients, and FECR was highly expressed in serum-derived exosomes from small cell lung cancer patients compared with that from healthy donors." (PMID 33292236, 2020).
lung carcinoma (8 papers, 2016 to 2025). "We used an immunohistochemical staining approach to identify the correlation between histological type of lung cancer and FLI1 expression." (PMID 28410216, 2017). "Using real time-PCR, we detected the expression of FLI1 mRNA in lung cancer cell lines." (PMID 28410216, 2017). "To investigate the role of FLI1 in SCLC, we first examined the expression of FLI1 in lung cancer by immunohistochemistry staining." (PMID 28410216, 2017). "In the same way, xenografted Tg(fli1:EGFP) transgenic models with human lung cancer cell lines were used to compare the effects of different known drugs, promoting these models as a real-time drug screening platform for clinical lung cancer patients." (PMID 35565373, 2022). "TGFBR2, FLI1, ERG and NTRK3 were shared DEmRNAs of hsa‐mir‐9‐1, hsa‐mir‐9‐2 and hsa‐mir‐9‐3, which suggested that mir‐9 might play a crucial role in LUAD by regulating these four lung cancer‐related genes." (PMID 30761256, 2019). "Furthermore, the zebrafish transgenic line Tg(fli1:EGFP) is commonly used to study the antiangiogenic capacity of drugs, such as Bevacizumab, a humanized anti-vascular endothelial growth factor (VEGF) antibody for the treatment of some solid cancers (such as breast and lung cancer)." (PMID 35565373, 2022).
acute lymphoblastic leukemia (7 papers, 2013 to 2025). Leukemia with an acute onset, characterized by the presence of lymphoblasts in the bone marrow and the peripheral blood. "The antibody also detected wild-type FLI1 in Acute Lymphoblastic Leukemia (ALL) MOLT-4 cells." (PMID 41283512, 2025). "The FLI1::EWSR1 gene fusion is a rare and atypical event in acute lymphoblastic leukemia (ALL), not typically classified among the canonical translocations driving the disease." (PMID 41228238, 2025).
desmoplastic small round cell tumor (7 papers, 2008 to 2023). Desmoplastic small round cell tumor (DSRCT) is an aggressive soft tissue cancer that typically arises in serous lined surfaces of the abdominal or pelvic peritoneum, and spreads to the omentum, lymph nodes and hematogenously disseminates especially to the liver. "The EWS-WT1 fusion associated with desmoplastic small round cell tumors (DSRCT,) and a truncated protein composed of the first 262 amino acids of FUS with a short tag were used as controls along with FLI-1 and ERG-1 proteins." (PMID 18648544, 2008). "As EWSR1 rearrangement may be found in other tumors such as desmoplastic small round cell tumors, a detection of fusion types (EWSR1/FLI-1 and EWSR1/ERG) from RNA is necessary to confirm the diagnosis using reverse transcription polymerase chain reaction (RT-PCR), which is a highly specific method." (PMID 30319719, 2018).
glioma (7 papers, 2014 to 2024). A benign or malignant brain and spinal cord tumor that arises from glial cells (astrocytes, oligodendrocytes, ependymal cells). "The second most commonly insertionally mutated gene in Rosa26-SB11 gliomas was Fli1 (6 total tumors)." (PMID 25423036, 2014). "Cloning insertions from these SB-induced gliomas identified Sfi1, Csf1, Mkln1, Vps13a and Fli1 as common insertion sites (CISs) which are chromosomal regions that are insertionally mutated in more tumors than would be expected by random chance and represent candidate glioma genes." (PMID 25423036, 2014). "For Fli1, all transposon insertions in gliomas are clustered in intron 1 or 2 in the same orientation of the gene and therefore are predicted to cause over-expression of a N-terminally truncated protein that contains the pointed and ETS domains." (PMID 25423036, 2014). "In the AR151 glioma, strong nuclear FLI1 immunoreactivity was detected in a subset of cells in the tumor adjacent to the dorsal third ventricle (brown staining)." (PMID 25423036, 2014). "We revealed that silencing circ‐USP1 could increase the BTB permeability via miR‐194‐5p/FLI1‐mediated regulation, which would provide a new therapeutic strategy of glioma." (PMID 31654502, 2020). "Overall, this present study identified the crucial regulation of circ‐USP1 on BTB permeability via miR‐194‐5p/FLI1 axis‐mediated regulation of tight junction proteins, which might facilitate the development of therapeutics against human gliomas." (PMID 31654502, 2020). "It is possible that FLI1+ cells in human gliomas would be regionally restricted and present in tumor biopsies utilized for genomics/expression studies, but not always detected in the small cores present in tumor microarrays utilized for immunohistochemical studies." (PMID 25423036, 2014). "Significant upregulation of Dusp6 and Fli1 gene expressions and downregulation of Hmox1 and Jun gene expressions in BV2 microglia, 2 h post segregated coculture with C6 glioma cells, were confirmed by RT-qPCR analysis." (PMID 39019900, 2024). "To further explore the involvement of Fli1 in SB-induced gliomas, we performed dual IHC for FLI1 and IBA1 (a marker for macrophages including brain resident microglia) on AR151, the glioma harboring an insertion in Fli1 for which FFPE material suitable for IHC was available." (PMID 25423036, 2014).
lupus nephritis (7 papers, 2010 to 2025). Glomerulonephritis in the context of systemic lupus erythematosus. "Promising data, however, highlight Fli-1 inhibitors as effective in ameliorating lupus nephritis in preclinical models, suggesting its therapeutic potential for inflammatory and autoimmune diseases." (PMID 40305194, 2025). "Further investigation is needed to clarify the association of Fli-1 in CCL20 expression and infiltration of CCR6+ Th17 cells in lupus nephritis." (PMID 32183259, 2020). "In our previous study we found that Fli-1 directly regulated IL-6 expression and promoted the progression of lupus nephritis." (PMID 32183259, 2020). "In this report, we investigate the impact of Fli-1 and its role in the development of lupus nephritis." (PMID 32183259, 2020). "The transcription factor Friend leukemia integration 1 (Fli-1) regulates the expression of numerous cytokines and chemokines and alters the progression of lupus nephritis in humans and in the MRL/MpJ-Faslpr (MRL/lpr) mouse model." (PMID 32183259, 2020). "High FLI-1 expression leads to lupus nephritis by promoting a local inflammatory state." (PMID 39107790, 2024). "Among the possibilities, there may be an indirect effect of Fli-1 in promoting the development of lupus nephritis." (PMID 32183259, 2020). "We previously reported that Fli-1 plays an important role in the development of lupus nephritis." (PMID 32183259, 2020). "The current study further supports our recent report that low doses of CPT or TPT inhibit Fli-1 and significantly attenuate lupus nephritis without liver toxicity or myelosuppression." (PMID 36074578, 2022).
colorectal cancer (6 papers, 2017 to 2024). A primary or metastatic malignant neoplasm that affects the colon or rectum. "DNMT3b accelerates promoter methylation of FLI1, resulting in the downregulation of FLI1 expression, which enhances proliferation, migration, and invasion of colorectal cancer (CRC) cells." (PMID 39044262, 2024). "Furthermore, FLI1 hypermethylation was identified in 65.7% of plasma samples obtained from colorectal cancer patients." (PMID 31675985, 2019). "The DLD-1 colorectal cancer cell line was chosen because it does not express EWSR1/FLI1 endogenously, and because it has a near-diploid karyotype, it has been used as a model to evaluate proteins of interest for their ability to induce aneuploidy." (PMID 33293370, 2021).
glioblastoma (6 papers, 2020 to 2025). The most malignant astrocytic tumor (WHO grade IV). "Among them, Fli-1 signaling is associated with the occurrence of GBM and is highly expressed in radiotherapy- and temozolomide-resistant glioblastomas, and can regulate HSPB1 at the transcriptional level." (PMID 40149733, 2025). "FLI1 is shown to promote glioblastoma radioresistance by regulating HSBP1, and its expression is associated with radiation resistance in oral squamous cell carcinoma." (PMID 36814284, 2023). "Overexpression of Fli1 promoted resistance to radiation exposure in glioblastoma cells." (PMID 39451223, 2024). "In addition, overexpression of FLI1 in glioblastoma cells promotes resistance to both radiation and temozolomide." (PMID 36814284, 2023). "Doxorubicin is an anticancer drug used to treat neural cancers, and exosome-encapsulated forms of this drug have been developed that can cross the zebrafish blood–brain barrier in Tg (fli1:EGFP) zebrafish and reduce xenografted U87 glioblastoma tumor volume." (PMID 37048068, 2023). "It illustrates that targeted inhibition of Fli-1/HSPB1-mediates EMT and ECM remodeling signaling axes by genetic (shRNAs/siRNAs) inhibitors can regulate GBM phenotype and might provide novel therapeutic reagents for radio/TMZR glioblastoma." (PMID 32284788, 2020).
lymph node metastasis (6 papers, 2015 to 2025). "High FLI-1 expression is significantly associated with advanced tumor stage, lymph node metastasis, and poor patient survival." (PMID 38280044, 2024). "There was a clear positive association between the FLI1 expression score and the percentage rate of lymph node metastasis." (PMID 26156017, 2015). "The univariate Cox analysis demonstrated that the OS of patients with high expression of FLI‐1 was relatively shorter (P < .001), which was similar to lymph node metastasis (P = .005) and advanced stage (P = .008)." (PMID 29869379, 2018). "Overall, these results showed that FLI‐1 positively correlated with lymph node metastasis and clinical stage." (PMID 29869379, 2018). "The immunohistochemical analysis showed that FLI‐1 was significantly related to the clinical late stage, lymph node metastasis, and reduced survival time (OS and DFS)." (PMID 29869379, 2018). "The FLI1 expression score is closely correlated with clinicopathologic features, including advanced stages and lymph node metastasis." (PMID 26156017, 2015). "Patients with FLI1 hypermethylation in cfDNA had more liver metastases (P = 0.042) and more paraaortic lymph node metastases (P = 0.021) than those without FLI1 hypermethylation." (PMID 31675985, 2019).
nasopharyngeal carcinoma (6 papers, 2017 to 2024). A carcinoma arising from the nasopharyngeal epithelium. "Fli1 was found to regulate radiotherapy resistance through the PI3K/AKT signalling pathway in nasopharyngeal carcinoma." (PMID 39451223, 2024). "Interestingly, a previous study demonstrated IFN-γ-induced kynurenine activation and induction of inflammatory response by FLI1 in nasopharyngeal carcinoma." (PMID 39769192, 2024).